IL2RG (interleukin 2 receptor subunit gamma)
Diseases named in the same sentence as IL2RG in open-access papers (continued):
Sharing a sentence is not in itself a finding about the gene and the disease.
lymphopenia (3 papers, 2024 to 2025). Reduction in the number of lymphocytes. "This study aims to provide detailed phenotypes of F344-Il2rg KO, Rag2 KO, and Il2rg/Rag2 KO rats, shedding light on their overall health status, physiological parameters, and histopathological features in lymphoid organs correlated with the severe lymphopenia caused by Il2rg and Rag2 KO." (PMID 39731164, 2024). "During experiments, Il2rg KO, Rag2 KO and Il2rg/Rag2 KO rats showed decreased white blood cells and systemic lymphopenia, with reduced CD4+, CD8+ T cells and CD161+ NK cells." (PMID 39731164, 2024). "CD27+Ly6C− and CD27+Ly6C+ γδ T cells were sorted separately from naive mice and immediately injected into NOD;Rag1−/−;Il2rg−/− (NRG-SGM3) mice to investigate lymphopenia-driven expansion." (PMID 38816652, 2024).
myeloma (3 papers, 2021 to 2022). "Based on the favorable co-expression of CD38 and SLAMF7 antigen at high levels on MM, we tested hemibodies in vivo using myeloma xenografts and human peripheral blood mononuclear cells (PBMCs) in a humanized immunodeficient NOD SCID Il2rg−/− (NSG) mouse model." (PMID 33420283, 2021).
Obesity (3 papers, 2022 to 2025). Accumulation of substantial excess body fat. "On the other hand, adoptive transfer of small intestinal ILC2s (SI-ILC2) into Il2rg-/-Rag2-/- mice promoted HFD-induced obesity and subsequent adipose tissue inflammation." (PMID 35784368, 2022). "Obesity was induced in HFD-fed Rag2-/- mice (lacking T cells, B cells, and NKT cells but with ILCs or NK cells), but not in Il2rg-/-Rag2-/- mice (lacking all lymphocytes)." (PMID 35784368, 2022).
Omenn syndrome (3 papers, 2020 to 2025). An inflammatory condition characterized by erythroderma, desquamation, alopecia, chronic diarrhea, failure to thrive, lymphadenopathy, and hepatosplenomegaly, associated with severe combined immunodeficiency (SCID). "However, it negatively impacts patients with somatic variants in CARD11, RAG1, as well as in a reported case of IL2RG reversion in tissue infiltrating T-cells, all associated with Omenn syndrome." (PMID 40711587, 2025). "Our patients with IL2RG, RAG1/2, and AICDA mutations had Treg cell dysfunction causing lymphadenopathy and erythroderma (or severe atopic dermatitis) similar to Omenn syndrome, which is consistent with previous studies." (PMID 32670274, 2020). "SCID patients had disease-causing mutations in RAG1 or RAG2 (n = 4, two of them presented with Omenn syndrome), IL2RG (n = 4, one of them with confirmed maternal engraftment), NHEJ1 (n = 1), CD3E (n = 1), ADA (n = 1), JAK3 (n = 3, two of them with maternal engraftment) and DCLRE1C (n = 1)." (PMID 32265901, 2020).
periodontitis (3 papers, 2023 to 2025). An acute or chronic inflammatory process that affects the tissues that surround and support the teeth. "In this study, we further explored the role of ILC3s in periodontitis-associated bone loss using Rag2-/- and Rag2-/-Il2rg-/- mice." (PMID 38015204, 2023). "Therefore, our findings suggest that ILC3s, which are differentially impacted by Rag2-/-Il2rg-/- and Rag2-/- mutations, may be primarily responsible for human periodontitis-like cervical alveolar bone resorption near the site of gingival inflammation." (PMID 38015204, 2023). "The intersection of these three machine learning approaches revealed six potential biomarkers associated with PANoptosis in periodontitis: PECAM1, CXCR4, SELP, IL2RG, CD48, and ZBP1." (PMID 40612110, 2025). "In this study, seven genes (CD19, CXCR4, FABP4, FOS, IGHD, IL2RG, and PPBP) were significantly up-regulated in periodontitis samples." (PMID 39917706, 2024). "A total of 7 genes (CD19, CXCR4, FABP4, FOS, IGHD, IL2RG, and PPBP) were upregulated in periodontitis samples." (PMID 39917706, 2024).
type 1 diabetes (3 papers, 2012 to 2025). "Liraglutide was tested in immunodeficient NOD-Scid IL2rg−/− (NSG) mice with type 1 diabetes." (PMID 32477262, 2020).
viral infections (3 papers, 2014 to 2025). "As NK cells respond very early to virus infection, we reason that this loss of NK cells is responsible for the increased virus replication in the liver of Il2rg KO hamsters at 4 days post challenge." (PMID 32651192, 2020). "IL2RG has been shown to contribute to the immune response during secondary viral infections by promoting the swift entry of memory cells into the cell cycle and enabling IL-2 signal-dependent competitive proliferation." (PMID 40724541, 2025). "The Il2rg KO hamsters had only marginal levels of NAbs in the serum, whereas the wild-type hamsters produced high amounts, confirming that similar to T lymphocytes and NK cells, the functional reaction of B lymphocytes to virus infection is also impaired." (PMID 32651192, 2020). "To assess whether the defect in lymphocyte development in the Il2rg KO hamsters impairs the response to viral infections, we challenged these animals with an intravenous infection of HAdV-C6." (PMID 32651192, 2020). "Nevertheless, hamsters (and mice and rats) resemble humans in that Il2rg inactivation disrupted B cell function; no germinal centers formed in the spleen after virus infection and only a marginal amount of neutralizing antibody was produced after virus infection." (PMID 32651192, 2020).
acute myelogenous leukemia (2 papers, 2020 to 2023). "Our study supported the oncogenic role of WT1 in myeloid leukemia, and the highlight of this work is the discovery of new WT1 target genes, IL-2, IL-2RB, and IL-2RG, which are likely involved in WT1-mediated leukemogenesis in acute myelogenous leukemia." (PMID 33110919, 2020).
angioimmunoblastic T-cell lymphoma (2 papers, 2021 to 2022). A mature T-cell non-Hodgkin lymphoma, characterized by systemic disease and a polymorphous infiltrate involving lymph nodes and extranodal sites. "In contrast, polyclonal T-cells had up-regulation of genes related to HTLV-1 infection (NFKBIA and EGR1), cytokine interaction (CCL4 and IL2RG), apoptosis, and inflammatory response, as well as genes down-regulated in angioimmunoblastic T-cell lymphoma (AILT)." (PMID 35464471, 2022).
Artemis deficiency (2 papers, 2024 to 2025). "Sixpatients had ADA deficiency, 3 had IL2RG deficiency, 3 had CD3 Delta deficiency, 2 had Artemis deficiency (affecting DCLRE1C), and 1 each had variants impacting NHEJ1, TRAC, RAC2, and RMRP." (PMID 39062699, 2024).
autoimmune disorders (2 papers, 2020 to 2026). "Recognition of immune dysregulation, autoimmunity, and malignancy as part of the IL2RG-related spectrum has refined long-term follow-up protocols." (PMID 41909668, 2026).
breast tumor (2 papers, 2024). "When evaluating all genes available in TCGA (N = 20,530) the gene expression differences between immune-high and low breast tumors included immune response genes including T cell signaling (e.g., IL2RG) and function (e.g., GZMB)." (PMID 39149486, 2024). "The results showed that CCL5 and IDH2 were not significantly differentially methylated in BRCA, while CCR7, EZR, IL8, and IL2RG were hypermethylated in normal tissues, and FLT3, MAPK10, and MMP9 were hypermethylated in breast tumor tissues." (PMID 38438469, 2024). "In contrast, IL18, IL2RG, IL33 and MAPK10 were highly expressed in normal breast tissues, whereas they were expressed at low levels in breast tumor tissues (p < 0.001)." (PMID 38438469, 2024).
COVID-19 (2 papers, 2022 to 2025). A disease caused by infection with severe acute respiratory syndrome coronavirus 2. "Together, these findings suggest that IL3 and IL33 contribute to the upregulation of IL2RA and IL2RG on basophils in severe COVID-19." (PMID 41459501, 2025). "Similarly, the expression of IL2RG (CD132) was significantly elevated in severe COVID-19 patients (p < 0.001), whereas IL2RB (CD122) expression remained largely unchanged across the groups." (PMID 41459501, 2025). "Notably, we also observed marked upregulation of IL2RA and IL2RG on basophils in severe COVID-19 patients." (PMID 41459501, 2025).
endometriosis (2 papers, 2020 to 2025). The growth of functional endometrial tissue in anatomic sites outside the uterine body. "Studies had reported endometriosis was induced in BALB/c-Rag2(-/-) IL2RG (-/-) mice by surgical implantation of human endometrial fragments." (PMID 40830889, 2025).
liver failure (2 papers, 2019 to 2021). A liver disease characterized by the liver losing or has lost all of its function. "Here, Fah–/–Rag2–/–IL2rg–/– (FRG) rats are generated by CRISPR/Cas9, showing accelerated liver failure and lagged liver xeno‐repopulation compared to FRG mice." (PMID 34382351, 2021).
lung carcinoma (2 papers, 2013 to 2017). "In addition, DOK2, which is a downstream mediator of IL2RG, has been identified as a suppressor of lung cancer cell proliferation." (PMID 23451142, 2013).
lymphoproliferative disorder (2 papers, 2018 to 2019). "One patient with IL2RG defect developed a lymphoproliferative disorder not EBV-related, while a patient carrying DLREC1A biallelic genetic alterations developed an EBV-related large B-cell lymphoma of nasopahrynx." (PMID 31456805, 2019).
myelogenous leukemia (2 papers, 2014 to 2020). "For example, correction of a point mutation in interleukin 2 receptor, gamma (IL2RG) was accomplished in K562 cells, an immortalized myelogenous leukemia human cell line, as well as in primary human T-cells and human CD34+ cells." (PMID 25409432, 2014). "Based on the literature review, this study is the first report to show that WT1 can regulate the RNA expression of IL-2, IL-2RB, and IL-2RG in the myeloid leukemia cells." (PMID 33110919, 2020).
Nijmegen breakage syndrome (2 papers, 2020 to 2025). Nijmegen breakage syndrome is a rare genetic disease presenting at birth with microcephaly, dysmorphic facial features, becoming more noticeable with age, growth delay, and later-onset complications such as malignancies and infections. "Five had TRECs between zero and 5/μl and were immediately reported, and among them, one Nijmegen breakage syndrome (NBN) with SCID-like phenotype and three classical SCIDs (Artemis, JAK3, and IL2RG) were identified." (PMID 32754152, 2020).
psoriasis (2 papers, 2022 to 2025). An autoimmune condition characterized by red, well-delineated plaques with silvery scales that are usually on the extensor surfaces and scalp. "Four genes (SELP, CD93, VAV1, and IL2RG) were identified as the most reliable diagnostic indicators for psoriasis." (PMID 40539722, 2025).
adenovirus infection (1 paper, 2020). "As a result of the defective adaptive immune response, Il2rg KO hamsters developed a more severe human adenovirus infection and cleared virus less efficiently than immune competent wild-type hamsters." (PMID 32651192, 2020).
AIDS (1 paper, 2013). A syndrome resulting from the acquired deficiency of cellular immunity caused by the human immunodeficiency virus (HIV). "Small animal models for HIV-1 infection such as Rag2-/-/Il2rg-/- mice and BLT mice have made significant contributions to our understanding of HIV/AIDS pathogenesis." (PMID 24381568, 2013).
alcoholism (1 paper, 2021). "In addition to IL2RG, the study also revealed the role of alcoholism in GC pathogenesis and progression which has been debated for a long time as reflected by inconsistent investigation results." (PMID 33542731, 2021).
alopecia areata (1 paper, 2026). Loss of scalp and body hair involving microscopically inflammatory patchy areas. "Compared with healthy controls, mRNA levels of EOMES, GZMA, IL2RB, and IL2RG were significantly upregulated in alopecia areata (AA) lesional scalp (all p<0.01), whereas androgenetic alopecia (AGA) scalp showed no significant increase relative to controls (all p>0.05)." (PMID 41602548, 2026).
Arthritis (1 paper, 2023). Inflammation of a joint. "DACLIZUMAB is a specific IL2 receptor-targeting drug, which is related to GZMB, IL2RB, and IL2RG, and research indicates its therapeutic potential in the experimental arthritis model induced by CIA." (PMID 38046810, 2023).
Ataxia (1 paper, 2025). Ataxia refers to impaired coordination of voluntary muscle movement. "The difference between age of onset of ataxia in Ndufs4(-/-)/Il2rg(KO) mice and Ndufs4(-/-)/l2rg(WT) mice was statistically significant, but so small it is unlikely to be biologically meaningful." (PMID 40493653, 2025).
atopic asthma (1 paper, 2021). An asthma that is characterized by symptoms that are triggered by an allergic reaction caused by inhaled allergens such as dust mite allergen, pet dander, pollen and mold. "We speculate that IL2RG and CCL4 might be important genes related to childhood atopic asthma, and together with CCL2 participate in the cytokine receptor interaction signaling pathway that plays a role in childhood atopic asthma." (PMID 34525985, 2021).
B cell deficiency (1 paper, 2020). A broad classification of disorders where circulating numbers of B lymphocytes are decreased or ineffective. "We analyzed the functional requirement for these cells in RIHD using a genetic model of T- and B-cell deficiency (interleukin-2 receptor gamma chain knockout (IL2RG−/−)) and observed a complex role for these cells." (PMID 32316187, 2020).
bone tumour (1 paper, 2025). "We developed a novel orthotopic and humanised bone tumour microenvironment model in highly immunocompromised Il2rg and Rag2 double knockout rats." (PMID 41315643, 2025).
cardiac hypertrophy (1 paper, 2020). "Surprisingly, while IL2RG deficiency conferred protection from cardiac hypertrophy, it worsened heart function via echocardiogram three months after a large single RT dose, including increased end-systolic volume (ESV) and reduced ejection fraction (EF) and fractional shortening (FS) (p < 0.05)." (PMID 32316187, 2020). "Cardiac hypertrophy was observed in female immune-competent rats only, compared to male competent, or male or female IL2RG−/− rats." (PMID 32316187, 2020). "We examined whether the SS WT male rats or SS IL2RG−/− male and SS IL2RG−/− female rats exhibited cardiac hypertrophy five months post-24 Gy versus sham RT." (PMID 32316187, 2020). "The SS WT male rats do not experience statistically significant cardiac hypertrophy six months after RT, nor do the SS IL2RG−/− male rats." (PMID 32316187, 2020). "Additionally, the SS IL2RG−/− rats did not exhibit hypertrophy after RT compared to sham treatment, although the SS WT female exhibited cardiac hypertrophy at five months post-RT." (PMID 32316187, 2020).
CHARGE syndrome (1 paper, 2024). CHARGE syndrome is a multiple congenital anomaly syndrome characterized by the variable combination of multiple anomalies, mainly Coloboma; Choanal atresia/stenosis; Cranial nerve dysfunction; Characteristic ear anomalies (known as the major 4 C's). "However, OS has also been described in other genetic aetiologies that impair lymphocyte development, including IL7RA, IL2RG, ADA, DCLRE1C, RMRP and LIG4 deficiencies, and CHARGE syndrome." (PMID 38598033, 2024).
clostridium difficile infection (1 paper, 2019). Symptomatic infection due to the spore-forming bacterium clostridium difficile. "Previous study demonstrated innate lymphoid cells were a critical role against Clostridium difficile infection based on data from Rag1-/- single gene and Rag2/IL2rg-/- double gene mutated mice." (PMID 31134127, 2019).
dysplastic nevi (1 paper, 2024). "Thirty days post-transplantation of dysplastic nevi, migration of donor melanophores was observed exclusively in the recipient skin of mitf−/−/prkdc−/−/il2rg−/−Xenopus tropicalis, but not in that of the mitf−/− frog." (PMID 38443437, 2024).
esophageal cancer (1 paper, 2024). A primary or metastatic malignant neoplasm involving the esophagus. "Among negatively correlated genes, a higher expression of CLDNI5 and IL2RG, and was seen in esophageal cancer than normal tissue (p < .05), but the converse was true for DGKD, CLDNI8, TMEM220-AS1, TMEM220, C3orf86, and SSR2 (p < .0.05)." (PMID 38241178, 2024).
heart failure (1 paper, 2020). Inability of the heart to pump blood at an adequate rate to meet tissue metabolic requirements. "Some of the SS rats died before the three- and five-month timepoints due to heart failure: two SS WT females before three months, three additional WT females before five months, two SS IL2RG−/− females before five months, and two WT SS males before five months." (PMID 32316187, 2020).
hyperandrogenism (1 paper, 2025). Excessive secretion of androgens from the adrenal glands or gonads. "In PCOS, the IL2RG/GSDME axis interacts with key pathways: hyperandrogenism signals through IL-2R, activating CASP3 which cleaves GSDME." (PMID 40830889, 2025).
iris disease (1 paper, 2014). "Our findings demonstrate that neither diminishing NK mediated cytotoxic activity (Prf1 mutation) nor NK cell depletion (Il2rg mutation) has any influence on the severity or timing of GpnmbR150XTyrp1b mediated iris disease." (PMID 24678736, 2014). "Therefore, any observed alteration of iris disease in Il2rg-/- mice would most likely reflect NK cell involvement." (PMID 24678736, 2014). "Neither the Prf1 or Il2rg mutations had any influence on the iris disease, which was indistinguishable from that of their wild-type littermates." (PMID 24678736, 2014).
Leigh syndrome (1 paper, 2025). A progressive neurological disease defined by specific neuropathological features associating brainstem and basal ganglia lesions. "This might indicate that the Ndufs4(-/-)/Il2rg(KO) mice are more frail than Ndufs4(-/-)/Il2rg(+/-) animals, which would be consistent with the possibility that adaptive immune depletion not only fails to prevent disease but is actively harmful to the Leigh syndrome model." (PMID 40493653, 2025).
lymph node metastasis (1 paper, 2020). "IL2RG exhibited significant negative correlation with lymph node metastasis." (PMID 33049716, 2020).
metastasis (1 paper, 2020). The spread or migration of cancer cells from one part of the body (where they first appeared) to another. "Moreover, expression of individual genes in this panel, including IL18RAP, CXCL11, FCER1G, CSF3R and IL2RG were strongly linked to distant metastasis, lymph node metastasis, tumor stage, clinical stage or pathologic grade." (PMID 33049716, 2020).
metastatic tumors (1 paper, 2013). "Injection of the thyrosphere-derived cells into the thyroids of NOD/SCID Il2rg-/- mice resulted in the formation of metastatic tumors that recapitulated the clinical features of human ATC." (PMID 23724124, 2013).
pancreatic adenocarcinoma (1 paper, 2021). "We have developed RAG2/IL2RG deficient pigs using CRISPR/Cas9 as a large animal model with the novel application of cancer xenograft studies of human pancreatic adenocarcinoma." (PMID 33828203, 2021).
plague (1 paper, 2016). Plague is a severe bacterial infection caused by the gram-negative bacterium Yersinia pestis. "Many of the genes identified in the present study, such as IL2RG, NdRG, IFNG, and CXCL6, were also regulated in the mouse pneumonic plague models." (PMID 27003632, 2016).
Pleural effusion (1 paper, 2020). The presence of an excessive amount of fluid in the pleural cavity. "Here, we also treated male SS WT rats and SS IL2RG−/− male and female rats with 24 Gy of localized cardiac RT and assessed pericardial and pleural effusion severity and quantity." (PMID 32316187, 2020).
pneumocystis pneumonia (1 paper, 2025). "The patient, SCID22, having an IL2RG gene mutation, had pneumocystis pneumonia and pulmonary aspergillosis prior to HSCT." (PMID 40457861, 2025).
Pruritus (1 paper, 2022). Pruritus is an itch or a sensation that makes a person want to scratch. "We identified several pruritus-associated genes increased by IDL, IDC and IDL + IDC (e.g., BRCA2, KRT5, TCF4), as well as several such genes decreased by IDL, IDC and/or IDL + IDC (e.g., IL2RG, TRPV3, TNFSF15, IL17RC)." (PMID 36430783, 2022).